RNU1-27P (RNA, U1 small nuclear 27, pseudogene)
Synonyms: RNU1-7; RNU1-7P
Gene: Small nuclear RNA gene on chromosome 14 (34,546,714 to 34,546,877, forward strand). Ensembl gene ENSG00000206596.
Homologues: Paralogues in human: RNU1-1 (100% identical), RNU1-2 (100% identical), RNU1-28P (100% identical), RNU1-3 (100% identical), RNU1-4 (100% identical), RNVU1-18 (100% identical), RNVU1-29 (100% identical), U1 (100% identical), RNVU1-28 (99% identical), RNVU1-7 (99% identical), RNVU1-31 (99% identical), RNU1-89P (97% identical), and 134 more.